STAP1 (signal transducing adaptor family member 1)
Diseases named in the same sentence as STAP1 in open-access papers (continued):
Sharing a sentence is not in itself a finding about the gene and the disease.
oncocytoma (1 paper, 2017). "The chRCC and oncocytoma samples displayed almost identical gene expression profiles for MAL, TMEM255A, RHCG, ATP6V0A4, STAP1, and DEFB1, as demonstrated by both RNA microarray and RNA sequencing, which is in agreement with the known fact that chRCC and oncocytoma are related neoplasms." (PMID 29208006, 2017).
periodontitis (1 paper, 2025). An acute or chronic inflammatory process that affects the tissues that surround and support the teeth. "Among them, HLA-C (IVW, nine SNPs, p=0.03) was identified as a risk factor for periodontitis, while STAP1 (IVW, four SNPs, p=0.01) and PTP4A3 (IVW, 10 SNPs, p=0.04) were recognized as protective factors." (PMID 40692979, 2025). "Further investigation revealed that key genes, including human leukocyte antigen C (HLA-C), STAP1, PTP4A3, NEU1, IGLV1-44, IGLL5, and NIPAL4, play critical roles in the pathogenesis of periodontitis." (PMID 40692979, 2025).
viral infection (1 paper, 2025). "USP18, STAP1, and OAS3 are involved in anti-viral response and have been shown to be upregulated in blood or lung tissue during viral infection." (PMID 41496780, 2025).
tumor (8 papers, 2017 to 2025). "STAP1 is a member of the signal-transducing adaptor protein family that functions importantly in immune response and tumor occurrence." (PMID 40936767, 2025). "As gene methylation is able to regulate the gene expression of itself, we analyzed the expression levels of STAP1 between primary tumor and solid normal tissue in TCGA data." (PMID 36713363, 2022). "In the context of DLBCL, overexpression of STAP1 enhances the sustained activation of the BCR-PI3K/AKT pathway, promoting tumor cell survival and inducing resistance to rituximab." (PMID 41189944, 2025).
cancer (7 papers, 2016 to 2024). A tumor composed of atypical neoplastic, often pleomorphic cells that invade other tissues. "Contrary to the previous genes, the products RGN, CAAP1, and STAP1, have been found to exert an anti-apoptotic effect and the disruption in their expression was reported in many cancers." (PMID 38978053, 2024). "We found that the cancer tissues displayed a lower methylation level of STAP1 than the adjacent tissues (by t-test, P < 0.05)." (PMID 36713363, 2022). "Similar to AHNAK, STAP1 methylation was also related to alcohol drinking, which suggests that these bad habits do affect the occurrence of cancer." (PMID 36713363, 2022). "That URI1 and STAP1 act as part of the URI1C to mediate survival of a subset of CRC cell lines suggests that certain cancer cells have evolved a specific dependency on this class of molecular chaperone complexes." (PMID 27105489, 2016). "Methylation level of STAP1 between cancer tissues and adjacent tissues." (PMID 36713363, 2022). "However, the involvement of the STAP1 protein in cancer thus far remains elusive." (PMID 33102522, 2020). "Although STAP1 and OBP2A remain inadequately investigation in TME or cancer related research, our results might provide some clues for further studies." (PMID 33552736, 2021).
bacterial infection (1 paper, 2025). "We showed that the median expression of certain genes (IFI27, HLA-DRB1, USP18, STAP1, and OAS3) in the Biomeme HR-B/V classifier was higher in viral versus bacterial infection." (PMID 41496780, 2025).
genetic disease (1 paper, 2024).
infection (1 paper, 2023). The state of being infected such as from the introduction of a foreign agent such as serum, vaccine, antigenic substance or organism. "Overall, StAP1 phage presents a broad infection spectrum and exhibits strong lytic effects on various MRSA strains, highlighting its tremendous potential as a powerful tool for MRSA infection treatment." (PMID 37840707, 2023). "Moreover, StAP1 exhibited excellent therapeutic effects against the tissue infection of MRSA." (PMID 37840707, 2023).
STAP1 also shares sentences with these, for which no sentence is quoted: chronic hepatitis B (2 papers); acute lymphoblastic leukemia (1); Autoimmunity (1); B-cell precursor acute lymphoblastic leukemia (1); Burkitt lymphoma (1); cardiovascular disease (1); chronic hepatitis (1); dyslipidemia (1); hepatitis C (1); immune diseases (1); infectious disease (1); kidney cancer (1); lung carcinoma (1); melanoma (1); staphylococcus aureus infection (1).